IGHV3OR16-17 (immunoglobulin heavy variable 3/OR16-17 (non-functional))
Synonyms: IGHV3/OR16-17
Gene: Immunoglobulin variable (V) gene on chromosome 16 (33,844,784 to 33,845,229, reverse strand). Ensembl gene ENSG00000259680.
Gene Ontology:
Molecular function: antigen binding
Biological process: immunoglobulin mediated immune response
Cellular component: extracellular region; plasma membrane
Homologues: Paralogues in human: IGHV3OR16-8 (98% identical), IGHV3-11 (86% identical), IGHV3-23 (83% identical), IGHV3-21 (81% identical), IGHV3-48 (81% identical), IGHV3-66 (81% identical), IGHV3-74 (81% identical), IGHV3-43 (79% identical), IGHV3-53 (79% identical), IGHV3-7 (79% identical), IGHV3OR16-10 (79% identical), IGHV3-20 (78% identical), and 65 more.